ZNF750 (zinc finger protein 750)
Diseases named in the same sentence as ZNF750 in open-access papers (continued):
Sharing a sentence is not in itself a finding about the gene and the disease.
breast carcinoma (5 papers, 2020 to 2023). "We have recently reported that ZNF750 inhibits the migratory and invasive properties of breast cancer cells by recruiting the epigenetic platform KDM1A/HDAC1 to the genetic loci of LAMB3 and CTNNAL1, ultimately repressing their expression." (PMID 37047491, 2023). "We have previously shown that low expression of ZNF750 predicts a worse disease-free survival compared to patients with high expression, independently from the breast cancer histotype." (PMID 37047491, 2023). "ZNF750 was recently described as an EMT repressor in breast cancer, an activity shared by OVOL2, TP63, and FOXO1." (PMID 38066300, 2023). "They showed that zinc-finger protein 750 (ZNF750) is a negative regulator of the migration and invasion of breast cancer cells." (PMID 36233261, 2022). "They showed that the expression of CTNNAL1 and LAMB3 contradictorily correlated with ZNF750 expression in a breast cancer model." (PMID 36233261, 2022). "We have recently found that RAC1 was upregulated after ZNF750 depletion in breast cancer cell lines." (PMID 33298895, 2020). "In particular, ZNF750 inhibits migration and invasion of the breast cancer cell lines by downregulating Wnt signalling." (PMID 33298895, 2020). "Here, we identify the axis ZNF750/RAC1 as a potential novel prognostic biomarker for predicting clinical outcome in breast cancer." (PMID 33298895, 2020). "Collectively, these data suggest that ZNF750 controls the expression of RAC1 in breast cancer cell lines." (PMID 33298895, 2020). "We have recently shown that ZNF750 negatively regulates cell migration, invasion and proliferation in breast cancer cells." (PMID 33298895, 2020). "In keeping, we showed that ZNF750 negatively regulates cell migration and invasion in breast cancer cells; in particular, ZNF750 binds and recruits KDM1A and HDAC1 on the LAMB3 and CTNNAL1 promoters." (PMID 33298895, 2020). "In agreement with this scenario, our findings provide evidences for a parallel and/or alternative molecular mechanism by which ZNF750 functions as tumour repressor in breast cancer." (PMID 33298895, 2020). "In agreement, ZNF750 expression negatively correlates with RAC1 expression in human breast cancer and in particular in luminal A subtypes." (PMID 33298895, 2020). "The expression of CTNNAL1 and LAMB3 inversely correlated with ZNF750 expression in breast cancer." (PMID 35879327, 2022). "Moreover, our findings highlight a possible alternative molecular mechanism by which ZNF750 functions as tumour suppressor gene in breast cancer." (PMID 33298895, 2020). "Interestingly, ZNF750 depletion resulted in a significant RAC1 upregulation in all the three breast cancer lines." (PMID 33298895, 2020). "In fact, we would like to speculate that besides repressing LAMB3 and CTNNAL1 expression, ZNF750 might also inhibit migration and invasion in breast cancer by repressing the expression of RAC1." (PMID 33298895, 2020). "In the current study, we show that the axis ZNF750/RAC1 may function as a potential biomarker for predicting patient survival in breast cancer." (PMID 33298895, 2020). "Hence, we report a potential clinical relevance of ZNF750/RAC1 axis in breast cancer." (PMID 33298895, 2020). "In keeping with ZNF750 controlling RAC1 expression, we found an inverse correlation between ZNF750 and RAC1 in human breast cancer datasets." (PMID 33298895, 2020). "They showed that zinc-finger protein 750 (ZNF750) is a negative regulator of the migration, and invasion of breast cancer cells by repressing a prometastatic transcriptional program, which includes genes involved in focal adhesion and extracellular matrix interactions, such as LAMB3 and CTNNAL1." (PMID 35879327, 2022). "Overall our data indicate that ZNF750 acts as tumour suppressor gene in breast cancer by negatively regulating the expression of RAC1." (PMID 33298895, 2020).
breast carcinoma (continued). "Importantly, they also showed gene expression analysis in cancer patient datasets which indicated that ZNF750, and its targets were negative prognostic factors in breast cancer." (PMID 35879327, 2022). "Additionally, they also showed gene expression analysis in cancer patient datasets that indicated ZNF750 and its targets to be negative prognostic factors in breast cancer." (PMID 36233261, 2022). "Given that ZNF750 is emerging as a crucial transcription factor that acts as tumour suppressor gene, here, we show that ZNF750 represses the expression of the small GTPase, Ras-related C3 botulinum toxin substrate 1 (RAC1) in breast cancer cell lines, by directly binding its promoter region." (PMID 33298895, 2020). "Thus, using the cBioPortal database, we asked whether the negative correlation between ZNF750 and RAC1 observed in breast cancer cell lines was also conserved in human breast cancer by using publicly available breast cancer datasets." (PMID 33298895, 2020).
esophageal cancer (5 papers, 2017 to 2024). A primary or metastatic malignant neoplasm involving the esophagus. "Our previous study showed that the transcription factor ZNF750 was also significantly decreased in esophageal cancer." (PMID 39730361, 2024). "Of the top 20 genes whose expression most correlated with ZNF750 expression in esophageal cancer, 10 were epidermal differentiation and keratinization-related genes, such as LYPD3, KRT6A, KRT16, and IVL." (PMID 37365152, 2023). "In consonance with our hypothesis, the high and low order of ZNF750 expression in the six esophageal cancer cell lines was consistent with GPR37." (PMID 39730361, 2024). "Therefore, we hypothesized that TRIM29 might positively regulate the expression of ZNF750 and mediate its inhibitory function in invasion and metastasis of esophageal cancer." (PMID 37365152, 2023).
seborrhea (5 papers, 2011 to 2024). "We have previously demonstrated that a dominant mutation in zinc finger protein 750 (ZNF750) causes seborrhea-like dermatitis with psoriasiform elements." (PMID 22936986, 2012).
dermatitis (4 papers, 2012 to 2024). An inflammatory process affecting the skin. "explains 28.07% of the total genomic variance and harbours the gene ZNF750 which encodes a putative C2H2 zinc finger protein which was shown to be associated with the skin disorders Seborrhoea-like dermatitis and familial psoriasis." (PMID 36624507, 2023).
melanoma (4 papers, 2023). A malignant, usually aggressive tumor composed of atypical, neoplastic melanocytes. "Another relevant gene in Molecular 1 group is ZNF750: its overexpression decreases proliferation of melanoma cells, whereas its depletion causes opposite effects.Molecular 1 comprised most of primary tumors included in the TCGA and GEM cohorts." (PMID 36614248, 2023). "Among most significantly altered genes, we selected INPP5J, ZNF750, and TUSC1 for further study because their gene products are known to reduce the viability and malignant proliferation of melanoma cells." (PMID 37293029, 2023). "Among the most significantly altered genes, we selected INPP5J, ZNF750, and TUSC1 for further study because their gene products are known to reduce the viability and malignant proliferation of melanoma cells." (PMID 37760992, 2023). "We then tested the impact of these dCas9-VprBP fusions on the transcription of INPP5J, ZNF750, and TUSC1 genes in G361 melanoma cells." (PMID 37293029, 2023). "Also supportive of the idea that VprBP modulates transcription at the level of initiation, dCAS9-VprBP was highly efficient in suppressing the transcription of INPP5J, ZNF750, and TUSC1 genes when guided to their promoter regions by sgRNAs in VprBP-depleted melanoma cells." (PMID 37293029, 2023).
cervical cancer (3 papers, 2019 to 2023). A primary or metastatic malignant neoplasm involving the cervix. "In a 16-year oncogene study, common epithelial squamous cell carcinomas (such as cervical cancer, head and neck cancer, and lung cancer) often exhibit ZNF750 deletion." (PMID 34187411, 2021).
lung carcinoma (3 papers, 2021 to 2024). "In vitro studies showed ZNF750 exhibited heightened expression in the normal lung epithelial cell line HBE compared to other lung cancer cell lines, and its expression was comparatively lower in LUSC cells than in LUAD cells." (PMID 38711034, 2024). "Furthermore, we employed RT-qPCR to validate the expression of genes regulated by ZNF750 in multiple lung cancer cell lines." (PMID 38711034, 2024). "Among them, GFI1B, HLF, and ZNF750 acted as protective factors of lung cancer prognosis." (PMID 34925645, 2021).
colon cancer (2 papers, 2022). "For colon cancer patients, the low expression of ZNF750 is significantly associated with a poor prognosis." (PMID 36358661, 2022). "Researchers have demonstrated that some ZFPs are vital in colon cancer progressions, such as ZNF545, KLF6-SV2, ZEB2-AS1, BORIS, and ZNF750." (PMID 36358661, 2022).
lung squamous cell carcinoma (2 papers, 2020 to 2021). "Similarly, the ratio of truncating and missense mutation was 3.93% (7/178) in lung squamous cell carcinoma (LUSC), however, there was no truncating or missense mutation of ZNF750 gene in lung adenocarcinoma (LUAC)." (PMID 32042337, 2020).
lymph node metastasis (2 papers, 2020 to 2021). "When ZNF750 mutations and deletions were combined, the associations with late stage (P = 0.006), more lymph node metastasis (P = 0.000453), and poorer survival (P = 0.016) were highly significant." (PMID 32341351, 2020). "The results showed that some genes were related to multiple clinical characteristics, such as ZNF750 related to lymph node metastasis and TNM stage." (PMID 35127817, 2021). "We found that individuals with mutations in ZNF750 had a more later stage, more lymph node metastasis and much worse prognosis than individuals without mutations." (PMID 32341351, 2020).
breast invasive carcinoma (1 paper, 2020). "We found a significant negative correlation between ZNF750 and RAC1 in all the breast invasive carcinoma datasets analysed." (PMID 33298895, 2020).
cutaneous squamous cell carcinoma (1 paper, 2021).
metastatic prostate carcinoma (1 paper, 2023). A carcinoma that arises from the prostate gland and has spread to other anatomic sites. "The possible role of ZNF750 as a reliable prognostic biomarker for metastatic prostate cancer is also supported by the literature." (PMID 37047491, 2023).
metastatic tumors (1 paper, 2023). "According to our results, the bioinformatics analysis showed that ZNF750 expression is significantly lower (p = 8.25 × 10−12) in both primary and metastatic tumors compared to normal tissues." (PMID 37047491, 2023).
oesophageal (1 paper, 2020). "Indeed, high levels of ZNF750 are associated with a good response to chemoradiotherapy in oesophageal SCC57." (PMID 33298895, 2020).
oral cancers (1 paper, 2025). "As described by Shigeishi (2023), in HPV-positive oral cancers, mutations in the PIK3CA gene are frequently observed, while there are somatic mutations in ZNF750, FGFR3, DDX3X, CASZ1, PTEN, and CYLD, differentiating them from HPV-negative oral cancers." (PMID 40284955, 2025).
prostate carcinoma (1 paper, 2023). A carcinoma that arises from epithelial cells of the prostate gland. "Moreover, our bioinformatics analysis points out that ZNF750 is also mutated in prostate cancer." (PMID 37047491, 2023). "Therefore, we asked whether in prostate cancer ZNF750 results also mutated." (PMID 37047491, 2023). "Both the mRNA and protein levels of ZNF750 are significantly reduced in prostate cancer cell lines compared to the normal cell line." (PMID 37047491, 2023). "The data reported here revealed that ZNF750 protein levels are reduced in human prostate cancer samples, and this reduction is even higher in metastatic samples." (PMID 37047491, 2023). "In this study, for the first time, a significant reduction in ZNF750 protein expression in acinar prostate carcinomas, both at the cytoplasmic and nuclear level, has been demonstrated." (PMID 37047491, 2023). "The results obtained from our patient cohort suggest that ZNF750 expression is reduced in patients affected by prostate cancer compared to the control group." (PMID 37047491, 2023). "Overall, the results reported here suggest that ZNF750 expression could potentially be a novel and reliable prognostic biomarker, which could be used to recognize prostate cancer with metastatic capacity." (PMID 37047491, 2023). "Starting from all these considerations, we have hypothesized a possible role for ZNF750 in prostate cancer." (PMID 37047491, 2023). "Overall, our findings suggest that nuclear expression of ZNF750 may be a reliable prognostic biomarker for metastatic prostate cancer, which lays the foundation for the development of new biological therapies." (PMID 37047491, 2023). "However, the levels of ZNF750 promoter methylation are comparable between the cell lines tested, suggesting that alternative molecular mechanisms are responsible for the downregulation of ZNF750 expression in prostate cancer cell lines." (PMID 37047491, 2023). "Logistic regression analysis was applied to identify the risk of prostate cancer metastasis formation associated with the Gleason score, grade group, and absence of ZNF750 nuclear staining." (PMID 37047491, 2023). "To further confirm the impairment of ZNF750 in prostate cancer, we assessed the expression of ZNF750 both in a normal prostate epithelial cell line (RWPE1) and in prostate cancer cell lines (PC3 and DU145)." (PMID 37047491, 2023). "More interestingly, the absence of ZNF750 nuclear staining may represent an important prognostic factor, since it is associated with a markedly increased risk of metastasis regardless of the traditional prostate cancer prognostic factors, such as the Gleason score and grade group." (PMID 37047491, 2023). "However, it is reasonable to think that assessing only the expression of ZNF750 in prostate cancer samples is not sufficient for predicting patient prognosis." (PMID 37047491, 2023).
skin cutaneous melanoma (1 paper, 2018). "In The Cancer Genome Atlas (TCGA) dataset, ZNF750 expression was significantly downregulated in ESCA, HNSC, and skin cutaneous melanoma (SKCM)." (PMID 30518868, 2018).
virus infection (1 paper, 2022). "Both Akata virus infection and AG876 virus infection decrease the expression levels of numerous different differentiation markers induced by methylcellulose suspension in uninfected NOKs, including K10, involucrin, GHRL3, ZNF750, KLF4, TGM1 and SPRR1A." (PMID 36190982, 2022).
tumor (40 papers, 2016 to 2025). "In our study, ZNF750 expression level was downregulated in high-risk group, which supported its protective role in inhibiting tumor progression." (PMID 36726580, 2023). "Downregulation of ZNF750 was consistent with previous studies showing that ZNF750 is expressed at a very low levels via truncating mutations and functions as a tumor suppressor in EC5,7." (PMID 34400640, 2021). "The loss of ZNF750 is related to impaired differentiation and failure to fully inhibit the proliferative genetic program, both of which are important markers of tumor." (PMID 34176441, 2021). "Although in the last few years several studies have highlighted the role of ZNF750 as tumour suppressor gene, the molecular mechanisms underlying the inhibition of cancer onset and progression are not well characterized." (PMID 33298895, 2020). "In this study, we revealed the tumor suppressive role of ZNF750 gene in ESCC and explored its underlying mechanism." (PMID 32042337, 2020). "We applied genome sequencing approaches, in vitro and in vivo methods to reveal the tumor suppressor role of ZNF750 and a possible novel mechanism underlying malignant phenotypes caused by loss-function of ZNF750 in ESCC." (PMID 32341351, 2020). "In the present study, we found that the poorly methylated gene ZNF750 (encoding zinc finger protein 750) was downregulated in NPC tumor tissues and cell lines." (PMID 30518868, 2018). "NOTCH1, CDKN2A, FBXW7, FAT1, and ZNF750 were considered as tumor suppressors and showed recurrent inactivating mutations." (PMID 29348864, 2017). "In this study, we found that loss-function of ZNF750 significant promoted tumor angiogenesis, which indicates anti-angiogenesis might be an efficient method in the inhibition of the growth and metastasis of ESCC with ZNF750 mutation or deletion." (PMID 32341351, 2020). "Together with several lines of functional evidences, ZNF750 may work in a loss-of-function manner and its dysregulation may be crucial for tumor formation and progression in ESCC." (PMID 32341351, 2020). "Taken together, the results suggested that ZNF750 gene may act as a tumor suppressor in ESCC and its inactivating-mutation or decreased expression may promote the malignant phenotype of ESCC cells, such as invasion, migration and so on." (PMID 32042337, 2020). "In our previous work, we sequenced the genome of 104 ESCC tumors tissues and the matched adjacent non-tumor tissues from individuals recruited from the Taihang Mountains in North-central China and found ZNF750 was one of the significantly mutated genes in ESCC5." (PMID 32042337, 2020). "Consistent with its in vitro functional role, clinicopathological analysis of LUSC revealed low expression of ZNF750 in tumor tissue juxtaposed with high expression of TNC." (PMID 38711034, 2024). "Conversely, ZNF750, a tumor suppressor in NPC, is destabilized by METTL3-mediated m6A modification, leading to reduced FGF14 expression and diminished apoptosis-promoting effects." (PMID 39695216, 2024). "While research on the interaction between ZNF750 and the Hippo pathway mainly focuses on outward migration of epidermal progenitor cells, the mechanism study of the regulatory role of ZNF750 in the Hippo pathway in tumor cells is rarely reported." (PMID 38711034, 2024).